MIR5702 (microRNA 5702)
Synonyms: hsa-mir-5702
Gene: MicroRNA gene on chromosome 2 (226,658,710 to 226,658,793, reverse strand). Ensembl gene ENSG00000263363.
Homologues: Orthologues: chimpanzee MIR5702 (100% identical).